GSDMD (gasdermin D)
Diseases named in the same sentence as GSDMD in open-access papers (continued):
Sharing a sentence is not in itself a finding about the gene and the disease.
infection (continued). "We observed a decrease in IL-1β, IL-6, TNF, and IFNβ levels in the supernatants of GSDMD knockdown (KD) macrophages despite comparable levels of infection as indicated by viral nucleoprotein levels in Western blots." (PMID 38553499, 2024). "We further investigated the mechanisms of host protection and the role of caspase-11 and GSDMD dependency during MDR A. baumannii 1605 infection." (PMID 39533032, 2024). "Only DBTRG cells exhibited a trend of increasing GSDMD cleavage following infection relative to mock-infected cells, but these differences were not statistically significant (p < 0.10)." (PMID 38308299, 2024). "Here, we investigate the function of the inflammasome-activated, pore-forming protein gasdermin D (GSDMD) during infection." (PMID 38553499, 2024). "We first examined lungs for GSDMD levels, including cleaved GSDMD N-terminal fragment indicative of activation, at day 7 post infection via Western blotting." (PMID 38553499, 2024). "Our in vitro results with THP-1 macrophages indicated that GSDMD depletion resulted in less secretion of pro-inflammatory cytokines following infection with the IAV PR8 strain or a seasonal H3N2 strain." (PMID 38553499, 2024). "Increased gasdermin D (GSDMD) expression during STm infection highlights cathepsin involvement in cell death through atypical inflammasome pathways." (PMID 39736788, 2024). "The role of GSDMD in macrophage pyroptosis is well-defined, but its involvement during infection with Leishmania has only recently been described." (PMID 39250503, 2024). "We identify NLRP1-driven GSDMD pyroptosis in neutrophils as critical in the control of the early neutrophil pool, impacting the outcome of infection." (PMID 39250503, 2024). "We observed that infection of CD18−/− BMDMs with the control strain induced lower levels of the cleaved form of caspase-1, IL-1β, and N-terminal Gasdermin D (N-GSDMD) compared to infection of WT BMDMs." (PMID 38724513, 2024). "Together, these results confirm that during L. mexicana infection in vivo, NLRP1-dependent caspase-1 activation of GSDMD, and subsequent pyroptosis control the neutrophil pool at the site of infection." (PMID 39250503, 2024). "We observed GSDMD cleavage following infection with both life stages, although much lower levels of GSDMD cleavage were observed after infection with amastigotes than promastigotes." (PMID 39250503, 2024). "Immunohistochemical staining revealed that the NLRP3 and GSDMD protein expression was elevated significantly (p < 0.01) in the infection group in contrast to the control group." (PMID 38515339, 2024). "When macrophages were infected with a high dose of DENV-1 (MOI = 1), NLRP3 and GSDMD mRNA reached a peak value in the early stage of infection (h.p.i = 24 h), while the Caspase-1 mRNA level gradually increased with the infection time." (PMID 39767659, 2024). "DBTRG and T98G cells infected with ZIKV exhibited gasdermin-D (GSDMD) cleavage, as detected by Western blot at late stage (day 5) of infection." (PMID 38308299, 2024). "Our results showed that GSDMD acted specifically in intestinal epithelial cells to combat the infection, independently of its effects on antimicrobial peptides or mucin secretion." (PMID 38807373, 2024). "Nonetheless, we were able to show that ectopically expressed GSDMD is cleaved in HCoV-229E infected cells, further suggesting that HCoV-229E Mpro can cleave GSDMD during infection." (PMID 38932190, 2024). "The critical role of neutrophil pyroptosis and its positive influence on the regulation of the disease outcome was further demonstrated following infection of mice with neutrophil-specific deletion of GSDMD." (PMID 39250503, 2024). "Human monocyte-derived macrophages expressed NLRP3 and infection with SARS-CoV-2 induced cleavage of IL-1 and GSDMD within eight hours post infection." (PMID 38664396, 2024).
infection (continued). "Collectively, our data shed further light on inflammasome activation and pyroptosis in neutrophils following infection with L. mexicana, showing a protective role for GSDMD through the regulation of the initial neutrophil niche population." (PMID 39250503, 2024). "Collectively, our data provides evidence that GSDMD plays a major role in augmenting cell death and hyperinflammation at the site of infection, thereby promoting severe IAV disease." (PMID 37945599, 2023). "The role of GSDMD during infection is likely cell type and pathogen specific, highlighted well in Pseudomonas aeruginosa lung infection models." (PMID 37266429, 2023). "For example, platelets significantly inhibited the expression of caspase-1 mRNA in macrophages at all DBV infectious doses at 72 h post-infection, while only reduced the expression of GSDMD when the DBV MOI was 0.1 or 0.0.1." (PMID 37486928, 2023). "In the early infection stage, the Spodoptera exigua host cells had high membrane permeability and cleaved gasdermin D (GSDMD) but uncleaved Casp-6 (SeCasp-6)." (PMID 36744941, 2023). "Taken together, our combined infection data from BM chimera and mice with cell-type-specific ablation suggest that both, epithelial and lamina propria cell GSDMD, contribute to restricting S.Tm tissue loads upon oral S.Tm infection." (PMID 37988464, 2023). "GSDMD-induced pyroptosis plays an important role in defending against pathogen infection and DAMPs stimulation by facilitating the removal of infected or damaged cells." (PMID 37275856, 2023). "We observed C. trachomatis infection induced-pyroptosis occurred most strongly at early infection as the greatest activation of GSDMD-NT was observed at 12 hours post infection." (PMID 37009510, 2023). "Baicalein attenuated infection-mediated acute liver injury by blocking NLRP3/GSDMD-mediated pyroptosis." (PMID 38022612, 2023). "Gasdermin D (GSDMD)-mediated pyroptosis and downstream inflammation are important self-protection mechanisms against stimuli and infections." (PMID 37275856, 2023). "E-cadherin+ epithelial cells lining the bronchioles and alveoli expressed cleaved GSDMD on day 3 post-infection, suggesting GSDMD is activated in lung epithelial cells in vivo during IAV infection." (PMID 37945599, 2023). "The cKp infection exhibited higher the fluorescence of cleaved GSDMD when compared to hvKp infection." (PMID 37457695, 2023). "GSDMD-mediated pyroptosis often triggers severe tissue inflammation during infections, immune diseases, or even cancers." (PMID 37495617, 2023). "Of note, at this time point of infection, in both GsdmD+/− and GsdmD−/− littermates, we measured high levels of the inflammatory marker lipocalin-2 (LCN2) in the feces." (PMID 37988464, 2023). "In recent years, the virulence mechanisms of some pathogens that maintain infection by preventing GSDMD-induced pyroptosis have been successively revealed." (PMID 37275856, 2023). "Previously published data demonstrated increased activation of the NLRP3 inflammasome, caspase-1, caspase-5, IL-1β, IL-18 and gasdermin D after infection of C. acnes-infected nucleus pulposus tissue." (PMID 36761775, 2023). "Monocytes and macrophages are sentinel cells that sense invasive infection to form inflammasomes that activate caspase-1 and gasdermin D (GSDMD), leading to inflammatory death (pyroptosis) and release of potent inflammatory mediators." (PMID 36741194, 2023). "The transcription factors IRF1 and IRF2 mediate non-canonical inflammasome activation by driving the expression of CASP4 and GSDMD genes at steady state and during infection." (PMID 38106412, 2023). "We detected GSDMD cleavage after 2 h infection, but after 24 h infection, we found a significant reduction in GSDMD cleavage." (PMID 36828815, 2023). "Gasdermin D (GSDMD) was recently identified as a mediator of pyroptosis-inflammatory cell death triggered by cytosolic sensing of invasive infection and danger signals." (PMID 37424923, 2023).
infection (continued). "A recent study demonstrated that nsp5 from different coronaviruses, SARS-CoV-2, MERS-CoV, PDCoV, and PEDV, can sustain their infection by suppression pyroptosis via pyroptosis by cleaving gasdermin D (GSDMD)." (PMID 37801439, 2023). "To confirm the occurrence of GSDMD-mediated pyroptosis during hvKp and cKp infection, we measured the GSDMD protein levels." (PMID 37457695, 2023). "Pyroptosis is a programmed cell death mechanism that is important for the body’s innate immune defense against infection and inflammation-induced tissue damage, which is mainly executed by gasdermin D (GSDMD)." (PMID 37859981, 2023). "GSDMD is a precursor of a pore-forming protein that exerts important effects on host defense against danger signals and pathogen infection." (PMID 37371484, 2023). "GSDMD was progressively activated with the ascending infection time and the greatest activation was observed at 12 hours post infection." (PMID 37009510, 2023). "Gasdermin D is particularly released in response to infection and/or injury, as well as an imbalance of homeostasis in the CNS." (PMID 37373482, 2023). "Platelets also suppressed the mRNA expression levels of pyroptosis-related genes (GSDMD and caspase-1) and displayed distinct modulation outcomes over the time of infection." (PMID 37486928, 2023). "The NLRP3 inflammasome can be activated by a variety of stimuli during infection, including potassium efflux downstream of caspase-4-dependent GSDMD activation and pore formation (5, –, 9)." (PMID 37615436, 2023). "We found that the Hsp90 inhibitor 17-DMAG can suppress macrophage cell death, active caspase-1, and GSDMD cleavage after SARS-CoV-2 GFP/ΔN infection." (PMID 37011862, 2023). "In future studies, it would be important to explore the role GSDMD-KO plays in infection, steroid exposure, and intermittent hypoxia-related BPD and ROP." (PMID 36599874, 2023). "Together, these studies reveal a role for GSDMD-mediated pyroptosis in a wide range of infections and in several viral infections where immune evasion strategies are coming to the fore." (PMID 35844522, 2022). "Infection with STEC O113 WT increased the cleaved form of GSDMD in J774.1 cells, whereas the cleavage was further promoted during infection with STEC O113 ΔsubAB." (PMID 35345462, 2022). "Upon activation by cytosolic danger and infection sensors in macrophages and dendritic cells cleave GSDMD within the linker region, liberating the active NT pore-forming domain to assemble GSDMD pores in the cell membrane." (PMID 35795683, 2022). "On the contrary, the bubble-like protrusions of GSDMD-/- macrophages cannot be observed after infection." (PMID 36311722, 2022). "Infection induced activation of inflammatory caspases and production of pro-inflammatory IL-1β and cleaved GSDMD, leading to pyroptosis of alveolar epithelial cells and alveolar macrophages." (PMID 35271686, 2022). "While the levels were increased by DOX administration, the increase was reduced in the GSDMD-CKO background, and partially rescued by AAV9-GSDMD-OE infection." (PMID 36289195, 2022). "We next quantified Caspase-1, Caspase-11 and Gasdermin D (GSDMD) cleavage by immunoblotting in wild-type (WT) BMDMs 12 hours post infection." (PMID 36318583, 2022). "In canonical pathway, inflammasomes such as NLRP3, NLRP4 and AIM2 are responsible for recognizing extracellular pathogens infection and then activate the caspase-1, which cleaves GSDMD into the N-terminus and C-terminus fragments later." (PMID 35573789, 2022). "The results showed that Ms_PE_PGRS19 induced more cleaved GSDMD N-terminal fragments (35 kDa) in macrophages after 4 and 6 h of infection compared with Ms_Vec and relative intensity data showed that the change was significant at 4 h." (PMID 36557726, 2022). "The extrinsic apoptotic pathway activates caspase-8, which can cleave GSDMD to elicit lytic cell death during infection of cells with Yersinia spp." (PMID 35844522, 2022).
infection (continued). "While largely detrimental in sterile inflammation, with some exceptions, GSDMD-induced cell death is as an important protective mechanism that regulates pathogen clearance during infection." (PMID 35455985, 2022). "The results show that Nlrp6−/− mouse macrophages secreted less GSDMD than WT macrophages during infection, which demonstrates that NLRP6 is involved in the modulation of pyroptosis." (PMID 36224650, 2022). "We further examined PBMCs infected with SFTSV at an MOI of 1 and detected the expression of GSDMD and an increase of its cleaved form, GSDMD-N, after infection." (PMID 35173184, 2022). "This study investigated the protective role of GSDMD in mice infected with SEZ and examined the role of GSDMD in peritoneal macrophages in the infection." (PMID 36311722, 2022). "Meanwhile, more multinucleated macrophages were observed in the spleen of GSDMD+/+ and GSDMD-/- mice after infection than in control." (PMID 36311722, 2022). "Again, GsdmD-/- neutrophils showed strong resistance to DNA decondensation upon PP34ExoUS142A infection." (PMID 35849616, 2022). "Furthermore, we observed here that mice deficient for caspase-8 and GSDMD are more susceptible to Brucella infection in vivo compared to wild type animals, suggesting that pyroptosis triggered during B. abortus infection is an important mechanism to control infection." (PMID 36532444, 2022). "The infection of casp-1−/− and gsdmd−/− cells confirmed that Kp52145-induced cell death was caspase-1 and GSDMD dependent." (PMID 35947948, 2022). "The recent development of selective ESX-1 inhibitors such as BTP15 allowed us to conditionally shut down secretion of ESX-1 effector proteins 5 h after infection of GSDMD knock-out macrophages." (PMID 34718331, 2021). "Consistent with previous studies, caspase-1/11 and GSDMD were required for host protection against infection at this infectious dose." (PMID 34154417, 2021). "Infection with C. albicans triggered robust cleavage of full-length GSDMD and generated the active N-terminal fragment in mouse bone marrow-derived macrophages (BMDMs), indicating direct activation of GSDMD by C. albicans." (PMID 34795266, 2021). "Pyroptosis, an inflammatory programmed cell death mediated by gasdermin D (GSDMD), is triggered by cytosolic sensing of invasive infection and danger signals." (PMID 34732218, 2021). "Pyroptosis and GSDMD activation are observed in the context of infection with other coronaviruses, such as SARS-CoV-2 and MHV." (PMID 35100869, 2021). "In contrast, repression of the transcription of GSDMD and NLRP3 indeed decreased host cell survival (GSDMD P value = 0.0038; NLRP3 P value = 0.0185), and GSDMD gene knockdown increased intracellular pathogen growth in S. flexneri ΔvirG infection." (PMID 34933448, 2021). "Hallmarks of cell death and inflammation, including cleaved caspase-1 and −3, gasdermin-D, neutrophil elastase, catalase, complement C3, and myeloperoxidase were validated in lung tissues on day 6 after infection via immunoblot." (PMID 34319784, 2021). "By day 2, the GSDMD−/− mice had significantly more macrophage and neutrophil infiltration than the WT mice at the site of infection." (PMID 34011393, 2021). "The GSDMD−/− mice had an increased bacterial burden in the skin compared to the WT mice on day 2 and on day 1 post-infection." (PMID 34011393, 2021). "The highest expression of GSDMD at 6 h post-infection indicated that pyroptosis was the most severe at this time." (PMID 33678162, 2021). "In TLR2−/− mice, the pyrolysis-related proteins (GSDMD, IL-1α, and IL-1β) upregulated, which showed the immunocompetence in the infection of A. fumigatus." (PMID 34222495, 2021). "As such, GSDMD can play a conflicting role during in vivo infections by promoting cytokine production, immune cell recruitment and tissue damage while restricting bacterial infection." (PMID 33441602, 2021).
infection (continued). "Mtb activated the canonical NLRP3 inflammasome by inducing potassium efflux upon the infection of monocytes and macrophages, followed by the GSDMD-dependent pyroptosis." (PMID 34163438, 2021). "Western blot analysis of the cell lysates combined with the cell culture supernatants (total) demonstrate that infection with SS−/− mutants led to decreased cleavage of GSDMD, CASP1, and IL-1β." (PMID 33441602, 2021). "Macrophages infected with B. thailandensis undergo NLRP3-, NLRC4-, caspase-1-, caspase-11-, and GSDMD-dependent pyroptosis (52, –, 60), but the role of other cell death pathways during infection is poorly understood." (PMID 34154417, 2021). "In this study, we found that alphacoronavirus TGEV upregulated and activated GSDMD, resulting in pyroptosis after infection." (PMID 35100869, 2021). "The pyroptotic effector GSDMD serves a crucial role in immune response and host defense during pathogen infection." (PMID 33634141, 2021). "Compared to untreated cells, cells pre-treated with Casp3 inhibitor showed significant reduction in the cell death in both WT and GsdmD-/- BMDM during infection with either Mtb or ΔpknF mutant." (PMID 34324582, 2021). "In the meantime, the inflammasome effectors including caspase-1, IL-1β, and GSDMD largely increased at infection; whereas IL-18 decreased during infection." (PMID 34161342, 2021). "The expression of GSDMD mRNA in the infection groups was higher than that in the control group, significantly different at 6 and 9 h post-infection (P < 0.01)." (PMID 33678162, 2021). "Pyroptosis is an inflammatory form of cell death that occurs in response to pathogenic infection and is typically driven by caspase-1 (CASP1) and/or caspase-11 (CASP11)-mediated cleavage of gasdermin D (GSDMD), which drives death by generating membrane pores." (PMID 33397971, 2021). "In brief, we found that during infections and some other diseases, a mass of GSDMD was secreted from NCs and released into PE rapidly." (PMID 34163438, 2021). "Our data showed the activation of GSDMD, along with the phosphorylation of STAT3 and NF-κB, caused by P. aeruginosa, but the activation was abolished by the oprC deficiency strain infection." (PMID 32849593, 2020). "NLRP3 is a classic sensor and has been reported to drive GSDMD cleavage in response to pathogen infection; therefore, we investigated the roles of the newly discovered NLRs NLRP12 and NLRC4." (PMID 32295623, 2020). "Furthermore, GSDMD-independent secondary necrosis appears to contribute to the clearance of bacterial infection, as it could be shown that Gsdmd−/− mice are less susceptible to infection with Francisella novicida compared with Casp1- or Aim2-deficient animals." (PMID 32345661, 2020). "By contrast, the time courses of cytotoxicity, IL‐18 maturation, and GSDMD cleavage revealed that OspC3 prevented pyroptosis at 2 h post‐infection (Figs EV1C and EV5C)." (PMID 32657447, 2020). "Together, our data demonstrate that Mtb induces potassium efflux-driven activation of the canonical NLRP3 inflammasome upon infection of human monocytes and macrophages, followed by GSDMD-dependent pyroptotic cell death with release of IL-1β." (PMID 32385301, 2020). "We found a significant increase in cleaved gasdermin D 24 h post-infection in the wildtype BMDMs compared to the significantly reduced levels observed in the Asc−/− macrophages." (PMID 33266295, 2020). "Complementation of VPRH restored all of the inflammasome-mediated phenotypes upon BMDM infection, including rapid cell death, IL-1β secretion, as well as cleavage of caspase-1, maturation of IL-1β, and cleavage of GSDMD." (PMID 32013758, 2020). "We therefore performed Western blotting analyses showing that MNV-infected BMDMs displayed GSDMD processing to its p30 fragment starting at 12 hours post-infection, in line with previously observed kinetics of inflammasome activation." (PMID 31017981, 2019).